SOST (sclerostin)
Diseases named in the same sentence as SOST in open-access papers (continued):
Sharing a sentence is not in itself a finding about the gene and the disease.
myeloma (continued). "The role of sclerostin in myeloma is clearly complex, and these contrasting conclusions may be due to sclerostin levels fluctuating depending on the severity of MBD and the timepoint at which they are measured in the disease course." (PMID 39108360, 2024). "Serum sclerostin levels are increased in hematological cancers such as multiple myeloma." (PMID 37174109, 2023). "Consistent with this, the pharmacological inhibition of sclerostin is accompanied by suppression of bone resorption in some mouse models of multiple myeloma and metastatic breast cancer, although the effect may vary across different models." (PMID 37174109, 2023). "First, previous studies have reported that serum sclerostin levels are elevated in patients with osteolytic changes in multiple myeloma and bone metastases from breast cancer, and that the administration of anti-sclerostin antibody suppresses bone destruction in model mice." (PMID 34885123, 2021). "Future evaluations are needed to determine whether the use of anti-sclerostin antibodies in patients with multiple myeloma affects tumor size." (PMID 31698687, 2019). "Administration of an anti-sclerostin antibody in a mouse myeloma model improved bone lesion." (PMID 31698687, 2019). "Furthermore, it has been demonstrated that instead of inducing apoptosis of osteoblasts, myeloma cells suppress osteoblast differentiation leading to increased sclerostin." (PMID 31698687, 2019). "In conclusion, all these data suggest that osteocytes are involved in myeloma bone disease and may be considered a novel target for the use of antibody-mediated anti-sclerostin therapy also in multiple myeloma patients." (PMID 30410490, 2018). "Serum sclerostin level is elevated in multiple myeloma, an osteolytic malignancy, where it might serve as predictive marker for the use of sclerostin-directed antibodies." (PMID 27666393, 2016). "The mechanisms regulating sclerostin production in multiple myeloma-bearing bones remain unclear." (PMID 37174109, 2023). "Clinical studies reported that serum levels of sclerostin positively correlate with the progression of multiple myeloma as well as those of macrophage inflammatory protein-1α which is secreted from multiple myeloma plasma cells and involved in the development of myeloma-related bone diseases." (PMID 35563281, 2022). "Thus, roles of sclerostin in the development of multiple myeloma have been controversial." (PMID 35563281, 2022). "Interestingly, treatment with an antiresorptive agent (zoledronic acid) and an anabolic drug (anti-SOST antibody) increased bone strength in preclinical myeloma models and may provide a rationale for relevant clinical studies." (PMID 33809268, 2021). "Therefore, sclerostin monoclonal antibody could be beneficial to reduce myeloma and breast cancer-mediated complications in bone." (PMID 32733380, 2020). "Interestingly, multiple myeloma cells and breast cancer cells also produce sclerostin that might have a catabolic effect on bone." (PMID 32733380, 2020). "LDN and BMPR1a-FC could inhibit Dkk1 expression in bone marrow mesenchymal stem cells (BMSCs) from myeloma patients, but only BMPR1a-FC reduced sclerostin levels in the bone marrow plasma of myeloma-bearing mice, which may explain the stronger anabolic effect of BMPR1a-FC." (PMID 31586071, 2019). "Antibodies that neutralize DKK1 or sclerostin are in trials and may have beneficial effects to relieve the suppression of bone formation caused by these WNT inhibitors, which can be made by breast cancer cells and myeloma as well as by bone (osteocytes in the case of sclerostin)." (PMID 25757219, 2014). "In multiple myeloma, the increase in the apoptosis of osteocyte leads to RANKL and sclerostin overexpression." (PMID 38634076, 2024).
myeloma (continued). "Finally, our findings also suggest that combination of PDGFR inhibition and sclerostin neutralization could represent a powerful approach to rapidly increase bone mass and strength in patients with osteolytic lesions provoked by multiple myeloma or bone metastases involving excessive PDGFR activity." (PMID 38713511, 2024). "Intriguingly, sclerostin and RANKL secreted by osteocytes are significantly elevated in circulating serum of multiple myeloma patients." (PMID 37860014, 2023). "Some promising targets in development for bone anabolic therapy in myeloma include Dikkopf protein 1 (DDK1), sclerostin, activin A and transforming growth factor β (TGFβ)." (PMID 36072809, 2022). "Sclerostin levels has also been related to RANKL in pathological conditions, including multiple myeloma, and rheumatoid arthritis." (PMID 35237949, 2022). "But the mechanisms by which myeloma cells regulate RANKL and sclerostin secretion from osteocytes have remained obscure." (PMID 35760800, 2022). "On the other hand, myeloma cells also respond to Wnt signaling pathway inhibitors, like dickkopf-1 (DDK-1) and sclerostin, which inhibit OB function." (PMID 32937821, 2020). "However, by causing a reduction in pathologically high sclerostin levels and so promoting osteoblast differentiation, whilst also inhibiting osteoclast development, pharmacological BMP inhibition has the potential to overcome the uncoupling of bone homeostasis that drives myeloma bone disease." (PMID 31586071, 2019). "In a mouse myeloma model with bone lesions generated by transplanting a human myeloma cell line into NOD-SCID mice, elevated blood levels of human DKK1 were observed, and while human sclerostin level was undetected, mouse sclerostin level was elevated." (PMID 31698687, 2019). "Interestingly, sclerostin and TGFβ are known drivers of PLR,8,14 both of which are known to be regulatory factors in myeloma." (PMID 39108360, 2024). "Increased serum sclerostin levels correlate with more extensive bone disease and negative myeloma features." (PMID 38247829, 2024). "One aspect we did not explore was circulating levels of DKK1 and SOST in both naïve and myeloma‐bearing conditions, and the influence of either single or combination strategies with anti‐LRP6 and anti‐DKK1 on these antagonists." (PMID 36987921, 2023). "In multiple myeloma models, activation of Wnt signaling via pharmacological inhibition of sclerostin one day after cancer cell injection or after 3 weeks did not affect tumor growth when tumors were established." (PMID 37174109, 2023). "An immunohistochemical study showed that myeloma cells were markedly decreased in these mice treated with anti-sclerostin antibodies and Carfilzomib, but not treated with only anti-sclerostin antibodies or Carfilzomib." (PMID 35563281, 2022). "So far, the administration of an anti-sclerostin antibody in a mouse myeloma model did not affect tumor mass." (PMID 31698687, 2019). "Most of the protein hits could be identified in blood samples according to the HPA database; two of them, namely DPEP1 and SOST, were classified by HPA as upregulated in BC; and five of them were found to be upregulated in leukemia and myeloma: SOST, TXNRD1, PKLR, EPHA2, PLIN3." (PMID 38791048, 2024). "However, in preclinical models of MBD, sclerostin inhibition has shown great promise, but as yet therapies such as romosozumab have not been used clinically in myeloma patients, only in osteoporosis." (PMID 39108360, 2024). "Unlike breast or prostate cancer cells, myeloma cells do not express sclerostin." (PMID 37174109, 2023). "Our study elucidates a molecular mechanism for the osteocyte-myeloma interaction, in which myeloma cell TP/2DDR upregulates CIITA expression in osteocytes; the increased CIITA enhances histone acetylation of TNFSF11 and SOST genes; and promotes RANKL and sclerostin secretion from osteocytes." (PMID 35760800, 2022).
myeloma (continued). "Additionally, myeloma cells modify the surrounding microenvironment and inhibit osteogenesis by direct secretion of Wnt antagonists, such as DKK-1, and by inducing the OB inhibitors, sclerostin, and activin, from mesenchymal cells and osteocytes." (PMID 32937821, 2020). "However, anti-sclerostin antibody did not affect tumor burden in vivo or the efficacy of anti-myeloma drugs in vitro." (PMID 30410490, 2018). "In a mouse model of bone metastatic multiple myeloma (MM), osteocytes and tumor cells physically interacted via dendrites, and this physical interaction was required for tumor cells to induce osteocyte apoptosis and increase levels of pro-resorption proteins RANKL and sclerostin." (PMID 30034365, 2018). "Remarkably, anti-sclerostin did not alter the anti-tumor effects of chemotherapy, suggesting that it could be used as an adjuvant therapy to improve bone health in patients with multiple myeloma." (PMID 37174109, 2023). "Similarly, the injection of myeloma cells in SOST KO mice did not affect myeloma progression." (PMID 37174109, 2023). "However, in a study including more than 630 myeloma patients, bone marrow plasma cell SOST mRNA expression was not different compared with healthy controls, nor was it detected in 56 human or murine myeloma cells lines, suggesting that the elevated serum Sclerostin was driven by another source." (PMID 30918922, 2019). "Unlike the DKK1/SOST dual antibody targeting two soluble antagonists, we chose to target both a membrane bound receptor and a soluble Wnt antagonist, DKK1, which is secreted by myeloma cells to suppress bone formation." (PMID 36987921, 2023). "Additionally, sclerostin concentrations within the bone marrow plasma of myeloma-bearing mice were significantly reduced by BMPR1a-FC in both 5TGM1 and JJN-3-myeloma-bearing mice, but not LDN193189." (PMID 31586071, 2019).
atherosclerosis (41 papers, 2017 to 2025). A disease characterized by the build-up of fatty material and calcium deposition in the arterial wall resulting in partial or complete occlusion of the arterial lumen. "Based on preclinical evidence that inhibition of sclerostin levels is involved in accelerating the vascular calcification process in atherosclerosis, which increases the risk of cardiovascular disease and mortality." (PMID 39808360, 2025). "Sclerostin is closely associated with vascular calcification and is present in several affected diseases such as hyperparathyroidism and atherosclerosis." (PMID 39808360, 2025). "After adjustment for major confounding variables, higher serum sclerostin levels were found to be independently associated with atherosclerosis in T2DM patients (p = 0.012)." (PMID 40429697, 2025). "The results showed a significant correlation between the severity of arterial stiffness and high levels of Sclerostin in PD patients, indicating that elevated serum Sclerostin levels are a risk factor for the progression of atherosclerosis." (PMID 38714960, 2024). "Two previous studies have used MR approaches to examine causal effects of sclerostin lowering on atherosclerosis and related risk factors." (PMID 37096546, 2023). "The goal of the present study was to examine potential safety concerns of sclerostin lowering on atherosclerosis and its risk factors using an MR approach, based on a set of instruments derived from an updated GWAS meta‐analysis of circulating sclerostin." (PMID 37096546, 2023). "Mendelian randomization (MR) was used to predict the causal effects of sclerostin lowering on 15 atherosclerosis‐related diseases and risk factors." (PMID 37096546, 2023). "Despite some conflicting studies, the majority of animal models suggest that sclerostin deficiency increases aortic aneurysm, atherosclerosis, and cardiac rupture, and have found its upregulation at sites of arterial calcification." (PMID 36776982, 2023). "This analysis allowed us to assess the association between sclerostin and atherosclerosis in a clinical context." (PMID 37919715, 2023). "The Steiger filtering analysis further confirmed that the sclerostin instruments were likely to first change the sclerostin level and then influence the atherosclerosis outcomes as a causal consequence." (PMID 37096546, 2023). "In this study, we aimed to establish the causal effects of lowering sclerostin, target of the antiosteoporosis drug romosozumab, on atherosclerosis and its risk factors." (PMID 37096546, 2023). "We used the 5 correlated cis‐acting SOST instruments to evaluate causal effects of lower sclerostin levels on 15 atherosclerosis‐related diseases and risk factors." (PMID 37096546, 2023). "The results showed that sex (p = 0.001), phosphorus (p < 0.001), and atherosclerosis (p = 0.001) were independently associated with serum sclerostin level." (PMID 32458213, 2020). "Although the causal relationship still needs further verification, sclerostin tends to affect cardiovascular outcomes by mediating the dynamic process of skeletal anabolism and atherosclerosis progression based on previous and current data." (PMID 31677125, 2020). "It was demonstrated that transgenic introduction of human sclerostin gene (SOST) and exposure to recombinant mice sclerostin in mice with ApoE−/− deficiency slowed down the formation of atherosclerosis and Ang II-induced AAA." (PMID 33336003, 2020). "In summary, sclerostin is related to atherosclerosis and all-cause mortality in patients undergoing MHD." (PMID 30314461, 2018). "Clinical and genetic research suggests that inhibiting sclerostin may increase the risk of cardiovascular diseases, as sclerostin produced in arterial tissue is thought to provide a protective mechanism against atherosclerosis." (PMID 40943516, 2025).
atherosclerosis (continued). "Additionally, we investigated the association between sclerostin levels and diabetic angiopathies, including DN as a microvascular complication and atherosclerosis as a macrovascular complication." (PMID 40353858, 2025). "This suggest that sclerostin may mitigate the susceptibility to atherosclerosis by decreasing atherosclerotic plaque related to improved cardiovascular risk factors such as LDL-c, calcium, and diastolic blood pressure." (PMID 37919715, 2023). "Therefore, there is a reasonable basis for considering that pharmacological inhibition of sclerostin carries a potential risk of accelerating atherosclerosis, leading to an increased risk of CVD." (PMID 37490188, 2023). "Further, sclerostin levels are thought to be associated with atherosclerosis in other vessel beds." (PMID 33800939, 2021). "Sclerostin has been proved to be linked with subclinical atherosclerosis." (PMID 32640551, 2020). "Bone metabolism dysfunction attributed to aging may initiate the loss of bone mass and downregulation of serum sclerostin levels, accelerating the atherosclerosis process in elderly SCAD patients undergoing PCI." (PMID 31677125, 2020). "The role of wnt signalling in atherogenesis raises the possibility that the wnt inhibitor, sclerostin, provides a natural defence to this process, and that anti-sclerostin antibodies might increase the risk of atherosclerosis and associated conditions such as CVD." (PMID 37490188, 2023). "Nonclinical studies in rodents indicated the inhibitory effect of sclerostin on inflammation, aortic aneurysm, atherosclerosis, and vascular calcification." (PMID 40429697, 2025). "Sclerostin expression in the tunica media of VSMCs in plaques from patients undergoing carotid endarterectomy, suggests a role in the development of atherosclerosis." (PMID 37919715, 2023). "Sclerostin has also been found highly expressed in calcified aortic tissue derived from human aortic samples from patients with atherosclerosis." (PMID 37919715, 2023). "This approach enabled us to examine the direct impact of sclerostin on VSMCs under conditions relevant to atherosclerosis development." (PMID 37919715, 2023). "Some studies reported a positive correlation between serum sclerostin level and subclinical atherosclerosis, atherosclerotic lesions and cardiovascular mortality in T2D population regardless of sex and age." (PMID 37919715, 2023). "In this context, a recent review reported a protective role of sclerostin against abdominal aortic aneurysms and atherosclerosis formation in preclinical models." (PMID 36498053, 2022). "Since accumulating evidence showed the important roles of the Wnt signaling pathways in pathogenesis of atherosclerosis, serum sclerostin was proposed to exert an endocrine role in atherosclerosis." (PMID 35546224, 2022). "Nevertheless, reports focusing on the role played by sclerostin in atherosclerosis were inconclusive." (PMID 35546224, 2022). "Here, our in vivo data showed that therapeutic sclerostin antibody elevated serum levels of inflammatory cytokines and chemokines, and aggravated AA and atherosclerosis in Col1a2+/G610C.ApoE-/- mice with AngII infusion." (PMID 35966595, 2022). "Further studies are required to push forward the role of sclerostin in the pathogenesis of atherosclerosis." (PMID 35546224, 2022). "Together, therapeutic sclerostin antibody elevated serum levels of inflammatory cytokines and chemokines, aggravated AA and atherosclerosis in Col1a2+/G610C.ApoE-/- mice with AngII infusion." (PMID 35966595, 2022). "Methods and Results: Our data showed that sclerostin suppressed inflammatory responses, prevented aortic aneurysm (AA) and atherosclerosis progression in hSOSTki.Col1a2+/G610C.ApoE-/- mice." (PMID 35966595, 2022). "SOST can inhibit the formation of aneurysms and atherosclerosis induced by Ang II, and regulating SOST can be used as a potential way to inhibit these diseases." (PMID 34901023, 2021).